ESM1 (endothelial cell specific molecule 1)
Diseases named in the same sentence as ESM1 in open-access papers (continued):
Sharing a sentence is not in itself a finding about the gene and the disease.
tumor (continued). "Furthermore, ESM1 is an EC biomarker that is strongly expressed in tumor ECs in several murine tumor models." (PMID 36248978, 2022). "However, direct evidence to demonstrate the role of ESM1 in tumor angiogenesis, particularly in anti-angiogenesis therapy resistance, requires further investigation." (PMID 36428773, 2022). "To further confirm that ESM1 could promote tumor lung metastasis, we injected 5 × 105 MDA-MB-231-S, MDA-MB-231-E, MDA-MB-231-R or shESM1-MDA-MB-231-R cells into balb/c-nu mice via the tail vein." (PMID 36428773, 2022). "However, after the bevacizumab-sensitive and bevacizumab-resistant cells were separated from tumor-bearing mice, ESM1 expression in drug-resistant cells was still stable and highly expressed, with 2.1 times that of sensitive cells." (PMID 36428773, 2022). "Moreover, HIF-1α/LOX induction and ESM-1 expression, which are involved in tumor metastasis and progression, were enhanced in CD24−/low/CD44+ cells compared to TNBC and RT-R-TNBC cells." (PMID 34502547, 2021). "ESM-1 plays an important role in tumor progression by regulating angiogenesis." (PMID 34500557, 2021). "Moreover, ESM-1 knockdown with short hairpin RNAs (shRNAs) dramatically inhibit the NGFR induced tumor growth, invasion, and metastasis in oral squamous cell carcinoma." (PMID 34109132, 2021). "According to in vitro experiments of human ACC cell line, SW13 cells, overexpression of ESM1 upregulated CDK1 and p21-mediated G2/M-phase transition, cell proliferation, cell migration, cell invasion, and accumulation of tumor mutation burden (TMB) via DLL4-Notch signaling pathway." (PMID 34858850, 2021). "Furthermore, ESM-1 can facilitate the transformation of dormant tumors into fast-growing angiogenic types and induce tumor formation." (PMID 34109132, 2021). "Several studies have reported a correlation between ESM1 expression and angiogenic processes during tumour progression, with ESM1 being crucial for vascular growth through the extracellular matrix, and have shown that high ESM1 levels are associated with increased risk of BC metastasis." (PMID 34298725, 2021). "However, N-cadherin, β-catenin, Snail, and ESM-1 expression levels were increased in RT-R-MDA-MB-231 tumor tissue compared to MDA-MB-231 tumor tissue and were even higher in CD24−/low/CD44+ tumor tissue." (PMID 34502547, 2021). "ESM-1 is over-expressed in tumor tissues but under-expressed in normal tissues." (PMID 34109132, 2021). "It is speculated that ESM-1 protein plays a role in the paracrine positive feedback loop and facilitates tumor growth." (PMID 34109132, 2021). "It has also been proposed that ESM1 synthesized by tumor endothelial cells may represent a good marker of angiogenesis and may even be a potential therapeutic target for angiogenesis." (PMID 35047401, 2021). "In addition, ESM-1 is involved in the tumor microenvironment, containing inflammation, angiogenesis, and lymph angiogenesis." (PMID 34109132, 2021). "ESM1 is a human endothelial cell-specific molecule synthesized by tumor endothelial cells." (PMID 35047401, 2021). "However, in contrast to Kcne3, which appears to be a universal ETC marker in multiple angiogenic contexts (retina, embryo, tumor), Esm1 loses ETC-specificity outside of the retina." (PMID 31754927, 2020). "ESM1 is preferentially expressed in tumor endothelium, and is dramatically overexpressed in many cancers including non-small cell lung cancer, colorectal cancer, clear cell renal cell carcinoma, gastric cancer, hepatocellular carcinoma, pituitary adenoma, ovarian cancer, and brain cancers." (PMID 31073279, 2019). "The authors considered that since human fully glycanated ESM1 could promote tumor growth, there was one interesting hypothesis regarding the balance between glycanated and non-glycanated ESM1, which could induce tumor growth or retardation." (PMID 28108731, 2017). "ESM1 is also known to be overexpressed in tumor cells themselves and can promote tumor growth." (PMID 27683113, 2016).
tumor (continued). "ESM1 functions to promote cell survival, cell cycle progression, tumor cell migration and invasion, and tumor angiogenesis and may serve as a tumor biomarker to predict survival of cancer patients, making ESM1 a potential therapeutic target." (PMID 24465615, 2014). "These genes are involved in the regulation of immune/inflammatory response (Lgals1, Ptgds, Tff2, Ubd), tumor angiogenesis (Lgals1, Esm1, Ndrg1), epidermal growth factor signaling (Erbb4, Nrg1), response to tissue injury (Tff2, Vnn1), and gene transcription (Id3, Ifrd1)." (PMID 19340302, 2009). "However, depletion of either CD4+ or CD8+T cells abolished the function of Esm1 on tumor growth." (PMID 38956432, 2024). "In addition, tumor results confirmed that ESM1 silencing reduced the p-PI3K/p-AKT expression." (PMID 38954708, 2024). "Moreover, Shikonin effectively counteracted the effect of ESM1 on tumor volume and weight." (PMID 38720298, 2024). "Endothelial-cell-specific molecule-1 (ECSM-1 or endocan) is a recently identified proteoglycan released from the vascular endothelium and associated with increased tissue expression, endothelial activation (inflammation), and neovascularization (tumor progression)." (PMID 36835804, 2023). "In addition, ESM1 plays an important role in tumor angiogenesis." (PMID 38201620, 2023). "In this study, we explored the underlying biological features of overexpressed ESM1 in human CSCC via the VEGFα/ERK signaling pathway to augment endothelial cell proliferation and tumor angiogenesis, suggesting that ESM1 may serve as a promising prognostic biomarker or therapeutic target for CSCC." (PMID 37476182, 2023). "In addition, in vitro assays with human CSCC cell lines, including SiHa and ME-180, demonstrated that knockdown of ESM1 expression inhibited tumor cell proliferation, migration and invasion, resulting in attenuated VEGFα expression and blocked phosphorylation of VEGFR2 and ERK-1/2." (PMID 37476182, 2023). "In addition, ESM1 is secreted primarily by endothelial cells in physiological homeostasis, and its content in normal body fluids is much lower than that in tumor patients; therefore, previous studies have focused on analyzing the relationship between ESM1 in body fluids and cancer prognosis." (PMID 36428773, 2022). "Therefore, we hypothesized that ESM1 may be a downstream molecule of TNFα that mediates bevacizumab resistance and further verified whether ESM1 was highly expressed in bevacizumab-resistant tumor tissues or cells." (PMID 36428773, 2022). "Moreover, ESM1 participates in tumor growth, migration, invasion, and angiogenesis." (PMID 36428773, 2022). "All in all, we conclude that silenced SNHG14 or elevated miR-211-3p depresses the proliferation, migration and invasion, and the tumor growth of nude mice, while facilitates the apoptosis of BCa cells, which may be connected with the down-regulated ESM1 expression." (PMID 33482820, 2021). "Moreover, ESM1 enrichment has been described in tip cells, and ESM1 downregulation characterizes the transcriptional switch of fast-growing angiogenic tumours to dormant tumours." (PMID 34298725, 2021). "Endocan, formerly known as endothelial cell-specific molecule 1, is a novel inflammatory marker which is secreted from vascular endothelium in addition to endothelial cells of various organs and plays a key regulatory role during the course of inflammatory diseases and neoplasms." (PMID 34912764, 2021). "ESM-1 expressed in the two types of tissue may both related to the change of tumor size." (PMID 31455321, 2019). "The precise role of ESM-1 in the regulation of tumor invasion should be investigated to clarify whether the structural or the functional regulation of tumor circulation environment involves, in addition, the actual stage of NCA in which ESM-1 affect also has to be evaluated in the future." (PMID 31455321, 2019). "Thus, ESM-1 may represent a novel tumor biomarker for the prognosis and prognostic of patients with NSCLC." (PMID 28514746, 2017).
tumor (continued). "In BC, endocan (ESM1), an endothelial-secreted PG containing GAG chains, has recently been identified as a promising candidate in blood to predict tumour burden and recurrence." (PMID 41463344, 2025). "Surprisingly, we found that ESM1 and PDGFB are expressed in the same tumor regions, while the distributions of PDGFA and PDGFC seem to be mutually exclusive with those of PDGFB and ESM1." (PMID 39773984, 2025). "The expression levels of ESM1 and ZEB1 in tumor tissues of AE treated group were decreased by qRT-PCR." (PMID 38954708, 2024). "qRT-PCR confirmed that silencing of ESM1 decreased the expression of ESM1 and ZEB1 in tumor tissues." (PMID 38954708, 2024). "Consistent with our in vitro findings, we observed increased expression levels of Ki67 and both Snail/Slug in tumor tissues from mice injected with NCI-N87/WT-ESM1, compared to mice injected with NCI-N87/Ctrl or NCI-N87/19del-ESM1." (PMID 39309430, 2024). "KM plot analyses from the same dataset revealed that GC patients with high ESM1 tumor expression had shorter overall survival (OS) (p = 0.011) and disease-free survival (DFS) (p = 0.042) times compared to those with low ESM1 tumor expression." (PMID 39309430, 2024). "Based on the results of bioinformatics analysis, we further confirmed the role of ESM1 and its effect on EMT of tumor cells through in vitro experiments." (PMID 38954708, 2024). "NCI-N87 cells overexpressing control vector (Ctrl), WT-ESM1, or 19del-ESM1 were subcutaneously injected into NOD-SCID mice, and sizes of tumor nodules were measured for 4 weeks." (PMID 39309430, 2024). "This occurs via TNF-α-induced expression of endothelial cell-specific molecule-1 (ESM1), which regulates matrix metalloproteinase 9, VEGF, and delta like canonical Notch ligand 4 (DLL4), thereby contributing to tumor metastasis." (PMID 39337337, 2024). "ESM1 can promote angiogenesis in colorectal cancer (CRC) by activating the PI3K/Akt/mTOR pathway, thereby accelerating tumor progression." (PMID 38201620, 2023). "It was revealed in this study that ESM1 promoted angiogenesis in CRC by activating the PI3K/Akt/mTOR pathway, thus accelerating tumor progression, consistent with previous studies." (PMID 37100467, 2023). "highlights six genes (VEGFA, KDR, ESM1, CD34, PECAM1, and ANGPTL4), but only four of them were expressed by endothelial cells while VEGFA and ANGPTL4 were mainly expressed by tumor cells." (PMID 36423636, 2022). "Tumor-promoting factors such as poly (ADP-ribose) polymerase (PARP) and endothelial cell-specific molecule-1 (ESM-1) can be down-regulated by siRNA in suppressing proliferation and migration of cancer cells, respectively." (PMID 34943856, 2021). "The results indicated that the expression of tumor cell-derived VEGFA, IGFBP3, EFNA1, EFNB1, IGF2, PDGFA and stroma-derived Angpt2, Cdh5, Esam, Esm1, Icam2, and Tie1 was statistically correlated with that of Pecam1 and elevated in p-EMT TW2.6 tumors." (PMID 34869001, 2021). "In brief, ESM-1 can enhance the function of other lymphangiogenic factors (such as VEGF-A, VEGF-C) to indirectly promote lymph angiogenesis and tumor metastasis." (PMID 34109132, 2021). "The non-glycanated mouse or human endocan polypeptide (previously known as endothelial cell specific molecule-1, ESM-1) restrains tumor growth by increasing leukocyte infiltration in vivo and enhancing innate immunity response." (PMID 34733848, 2021). "The expression of STC2, ESM1, INHBA, CXCL1 and TDGF1 was significantly increased in tumor tissues than in normal tissues, whereas GLP2R expression was higher in normal tissues than in tumor tissues." (PMID 32788867, 2020). "Meanwhile, we estimated tumor angiogenesis by detecting VEGFA, ESM-1 (endothelial cell specific molecule 1), and CD34 levels by ELISA assays." (PMID 28178668, 2017).
tumor (continued). "Cell proliferation is necessary for tumor cell growth, PC3 and DU-145 cells exhibiting stable ESM1 knockdown showed enhanced cell proliferation by MTT assay and increased colony formation ability by foci formation assays." (PMID 28108731, 2017). "Further, comparison of ESM1 expression in MOC2, MOC2-7, and MOC2-10 cells revealed a correlation with the extent of NGFR expression and the tumor growth kinetics and invasive phenotype observed in the MOC cell lines." (PMID 27683113, 2016). "In addition, ESM1 regulates the lymphocyte function-associated antigen-1 (LFA-1)/intercellular adhesion molecule-1 (ICAM-1) pathway; thus, it may play an important role in the migration of leukocytes into tumor tissues." (PMID 27683113, 2016). "Here, we used an established murine model of OSCC and gene expression array analysis to identify ESM1 as a downstream target gene of NGFR, critical for tumor invasion and metastasis." (PMID 27683113, 2016). "Subsequent RNA-sequencing (RNA-seq) revealed ESM1 as the most significantly upregulated gene in tumor-derived CD31+ cells compared to the non-neoplastic counterparts." (PMID 39773984, 2025). "Additionally, ESM1 and ETV4 are enriched in inflammatory and viral carcinogenesis pathways and play significant roles in remodeling the tumor microenvironment." (PMID 40722723, 2025). "ESM1 is significantly upregulated in tumor-derived vascular cells compared to non-transformed VE cells and its level correlates with higher grade and shorter survival in glioma." (PMID 39773984, 2025). "Interestingly, we found that ESM1 and PDGFB are expressed in the same tumor regions, while PDGFA and PDGFC seem to be mutually exclusive with PDGFB and ESM1." (PMID 39773984, 2025). "Conversely, ANGPTL4 inhibition significantly repressed the tumor weight and volume of SKOV3 cells with low vimentin, PCNA, MMP9, ESM1 and CD34 expression in comparison with the vector and NC groups, which could also be rescued by Colivelin." (PMID 38212795, 2024). "The aberrant expression of ESM1 in PTC could potentially interact with these oncogenic drivers, exacerbating tumor aggressiveness and resistance to standard therapies." (PMID 38626010, 2024). "ANGPTL4 overexpression could promote OC cell growth (tumor weight and volume) with higher expression of vimentin, proliferating cell nuclear antigen (PCNA), MMP9, ESM1 and CD34, which could be rescued by AG490." (PMID 38212795, 2024). "Herein, we reported, for the first time, that ESM1 activates the downstream MAPK pathway by binding to the membrane receptor c-Met on the surface of HUVEC cells to promote the production of HIF1α, VEGFA, and MMP9, eventually promoting tumor angiogenesis." (PMID 38201620, 2023). "In conclusion, ESM1 may promote angiogenesis in CRC by activating the PI3K/Akt/mTOR pathway, thus accelerating tumor progression." (PMID 37100467, 2023). "Besides, ESM1 and HIF-1α harbored synergistic functions in tumor angiogenesis and cell proliferation of CSCC cells via the VEGFα/VEGFR2/ERK signaling pathway based on in vitro experiments." (PMID 37476182, 2023). "Similarly, our results suggested that ESM1 is highly expressed in both CRC tumor cells lines and tumor tissues, with this high expression indicating a poor prognosis for CRC." (PMID 36518242, 2022). "Additionally, inhibiting ESM1 mRNA with siRNA reduces MMPs and epithelial-mesenchymal transition (EMT)-related gene expression, thus inhibiting tumor invasion in a colorectal cancer model." (PMID 36428773, 2022). "Furthermore, ESM1 deletion reduced CD31 levels in xenografts and was involved in decreased tumor angiogenesis." (PMID 36428773, 2022). "In addition to VEGF, ESM1 promoted MMP9, DLL4, and ICAM3 expression, indicating that ESM1 cooperated with VEGF to promote tumor development and promote bevacizumab resistance." (PMID 36428773, 2022).
tumor (continued). "IHC staining showed that the immunoreactivity of ESM1 was primarily expressed in the cytoplasm of tumor cells and not in normal esophageal squamous epithelial cells." (PMID 35937390, 2022). "Our results suggest that high levels of ATP released by RT-R-MDA-MB-231 cells may contribute to tumor progression by inducing P2Y2R activation and stimulating the P2Y2R-PAK1-FoxO1 signaling cascade to promote ESM-1 expression." (PMID 36077661, 2022). "Studies have shown that overexpression of ESM-1 in non-tumorigenic epithelial cells can induce tumor formation, while overexpression of ESM-1 in tumorigenic cells can significantly increase the growth rate of tumors." (PMID 34109132, 2021). "After treating with ESM1 siRNA in SK-Hep1 hapatocellular carcinoma cells, the cell cycle was arrested at the G1/S phase with down-expression of cyclin D1 and CKD4, but up-expression of PTEN, which had tumor suppressing function." (PMID 28108731, 2017). "Consistent with our hypothesis, ponatinib enhanced survival only of the tumor-bearing WT, but not Esm1 KO mice, and reduced blood vessel formation, as can be seen from both CD31 immunostaining intensity and quantification of the blood vessels diameter." (PMID 39773984, 2025). "Using Esm1 KO mice, we demonstrated that the absence of Endocan has a dramatic effect on both GBM cells and tumor-associated vasculature, suggesting that this protein might be one of the master regulators of GBM-VE crosstalk." (PMID 39773984, 2025). "Importantly, brain vascularization in the areas that did not contain tumor was not appreciably different between wild type and Esm1 knockout mice, as can be seen from CD31 staining and electron microscopy." (PMID 39773984, 2025). "However, as the patient tumor datasets contain a wide variety of cell types including immune, endothelial, and fibroblast cells, these cells were first removed from our analysis based on the expression of PTPRC (CD45), ESM1, and TAGLN respectively." (PMID 40241258, 2025). "Additionally, established tumor markers such as CEA (carcinoembryonic antigen), ESM-1 (endothelial cell-specific molecule-1), and SCC (squamous cell carcinoma antigen) are not fully applicable for clinical diagnosis of OSCC due to their limited sensitivity and specificity." (PMID 40538852, 2025). "Therefore, this suggested that ESM1 and HIF-1α might have synergistic roles in tumor angiogenesis and cell proliferation, and they might promote CSCC progression through the VEGFα/VEGFR2/ERK signaling pathway." (PMID 37476182, 2023). "ESM1 can activate the downstream MAPK/ERK signaling pathway by binding to the c-Met membrane receptor of vascular endothelial cells and can promote the expression of HIF1α, VEGFA, MMP9, and other pro-angiogenic factors, thereby promoting tumor angiogenesis and peritoneal metastasis." (PMID 38201620, 2023). "The GSEA analysis showed that ESM1 overexpression was associated with the co-expression of VEGFα and HIF-1α and was closely related to the VEGFα signaling pathway; ESM1 may regulate CSCC micro-angiogenesis and tumor progression via interaction with VEGFα and HIF-1α." (PMID 37476182, 2023). "They believed that since human fully glycosylated ESM-1 can promote tumor growth, there is an interesting hypothesis that the balance between glycosylated ESM-1 and non-glycosylated ESM-1 can induce or delay tumor growth." (PMID 34109132, 2021). "Indeed, in the in vivo xenograft model, CD24−/low/CD44+ cell-injected mice exhibited greatly increased tumor growth and lung metastasis, accompanied by upregulated expression of EMT-related proteins and increased HIF-1α and ESM-1 levels in tumors and circulating LOX levels in plasma." (PMID 34502547, 2021).